CALR (calreticulin)
Diseases named in the same sentence as CALR in open-access papers (continued):
Sharing a sentence is not in itself a finding about the gene and the disease.
melanoma (continued). "Calreticulin overexpression have also been reported in other malignant lesions such as esophageal squamous cell carcinoma, gastric cancer, pancreatic tumors, and even in melanoma cells." (PMID 27418879, 2016). "Furthermore, hepatocellular carcinoma, pancreatic malignancies, esophageal cancer, gastric cancer, colon cancer, melanoma, and leukemia have also been reported to be potentially correlated with calreticulin activity." (PMID 27418879, 2016). "Similarly, calreticulin associated with TRAIL, TRAILR2, as well as adaptor protein FADD and pro-caspase-8 in A375M melanoma cells." (PMID 25750898, 2015). "In near future, it would be interesting to find whether overall CRT or CALR levels in melanoma are predictive of clinical responses to ICD or immunotherapy and/or regulate overall levels/spatial distribution of CD8+ T cell-infiltrates." (PMID 26682274, 2015). "Opaganib increased calreticulin cell surface expression on all the cancer cells tested, with log responses ranging from 1.46 to 3.64, corresponding to ~3-fold to >400-fold increases in the pancreas, prostate, neuroblastoma, breast, lung and melanoma tumor cell lines." (PMID 38069222, 2023). "In the current study, CALR was found among proteins slightly overexpressed after HS conditioning (p value = 0.0259; logFC = 0.25), suggesting that HS treatment not only mobilizes this protein towards the plasma membrane of melanoma cells but also induces its expression by these cells." (PMID 29744371, 2018). "Moreover, we have also demonstrated that the HS treatment of melanoma cells before their final lysis for TRIMEL generation increases calreticulin (CALR) plasma membrane translocation and induces the release of high mobility group box 1 (HMGB1) protein and two well-described DAMPs." (PMID 29744371, 2018). "CD26 (DPP4) and CALR are involved in immune modulation and cell signaling, while B7-H3 (CD276) is a prominent immune checkpoint molecule highly expressed in melanoma and other tumors, contributing to immunosuppression and tumor progression." (PMID 40805206, 2025). "As a methodology, SFD is able to reveal well-known proteins in melanoma exosomes that are immune-related and are also surface-expressed proteins, such as CD26 (DPP4), CD44, CALR, B7-H3 (CD276), CSF1, ICAM1, L1CAM, MICB, APOH, TIMP1, and CD39." (PMID 40805206, 2025). "In more detail, initial studies have shown an increase in tumor immunogenicity following CAP treatment in in vivo murine melanoma models, including the upregulation of MHC-I and calreticulin." (PMID 35326381, 2022). "The influence of APP components on cancer cell sensitivity to immune pressure differs between the two cancer models, with ERAP1, calreticulin and TAPBPR more relevant in melanoma, and β2m in renal carcinoma." (PMID 35936007, 2022). "The objective of this study was to develop novel calreticulin nanoparticle (CRT-NP) and combine it with focused ultrasound (FUS) for ICD based immunomodulation in melanoma." (PMID 32206098, 2020). "P2Et-driven activation of PERK in melanoma cells was found to promote ER-calcium release, disrupt mitochondrial membrane potential, and trigger upregulation of ICD drivers, surface calreticulin expression, and extracellular release of ATP and HMGB1." (PMID 31531232, 2019). "Daunorubicin, which was utilized as a positive control for ICD, triggered robust induction of calreticulin, as well as of HLA-ABC, Hsp70 and PD-L1 in A375 melanoma cells." (PMID 30560089, 2018). "SK-MEL-28 (melanoma) and A549 (lung) were assayed for mRNA and protein level of ER chaperones [GRP78, GRP94, calreticulin (CRT)] and a cytosolic chaperone HSP70." (PMID 30038714, 2018). "Consistent with our in vitro findings, genes associated with the ATF4 (e.g., ATF4, DDIT3, PPP1R15A and CHAC1), ATF6 (e.g., ATF6B, CALR, SEL1L, and EDEM1) and XBP1 (e.g., SSR3 and DELR1) pathways were significantly enriched in melanoma TILs compared with healthy blood T cells." (PMID 40335738, 2025).
melanoma (continued). "A recent Phase I trial (NCT03784625) of melanoma-targeted radionuclide therapy showed that [131I]ICF01012 induces immunogenic tumor cell death, marked by a significant increase in cell surface Anxa1 and calreticulin." (PMID 33446132, 2021). "We demonstrated that low-dose doxorubicin chemotherapy upregulated expression of the pro-phagocytic signals calreticulin and phosphatidylserine, but failed to increase phagocytosis of melanoma cells." (PMID 31205227, 2020). "Next, we analysed the ecto-CALR levels in BNIP3WT or BNIP3KD melanoma cells (relative to normoxia or hypoxia)." (PMID 29707136, 2018). "Despite the absence of calreticulin induction, melphalan-exposed melanoma cells triggered protective immunity in a murine vaccination model." (PMID 30560089, 2018). "Although ICD in the context of targeted therapy for melanoma has not been thoroughly investigated, one study has shown that vemurafenib can promote cell surface exposure of calreticulin and HSP90 on various human melanoma cell lines." (PMID 29209327, 2017). "The exceptional ability of ApoV to protect against melanoma challenge could relate to products of “immunogenic cell death”, such as high mobility group box protein B1 (HMGB1) and calreticulin translocating to the ApoV pathway." (PMID 27462921, 2016). "In addition, the expression ER chaperones GRP78, GRP94, CALR, calnexin and PDI was dose- and time-dependently up-regulated after exposure to 11-dehydrosinulariolide in melanoma cells." (PMID 23015779, 2012). "Nevertheless, the apparent dispensability of CD47 and the absence of ecto-CALR, despite on-going phagocytosis, may be a sign of B16-F10 melanoma cells utilizing either alternative ‘don’t eat me’ signals or highly potent ‘eat me’ signals capable of circumventing ecto-CD47." (PMID 29707136, 2018). "Hence, it is proposed that the up-regulations of the ER chaperones calnexin, CALR and PDI after exposure to 11-dehydrosinulariolide are likely self-rescuing responses of the tumor cells or the onset of ER stress-mediated apoptosis induced by the treatment in the melanoma cells." (PMID 23015779, 2012).
polycythemia vera (46 papers, 2015 to 2026). "This study investigated the nuclear export activity of wild-type CALR in erythroid progenitors from patients with Polycythemia Vera carrying the JAK2V617F mutation." (PMID 29218307, 2017). "The result we obtained suggests that patients with JAK2, CALR, or MPL mutation-positive ET may have polycythemia vera." (PMID 35444868, 2022). "Two cases of Polycythemia Vera were negative for CAL2IHC, and were also concordant with negative Calreticulin mutation." (PMID 34514582, 2022). "While only exceptional cases of CALR-mutant polycythemia vera (PV) have been described in cases that were negative for JAK2V617F, 15–24 % and 25–35 % of patients with ET and PMF, respectively, carry a CALR mutation." (PMID 27177927, 2016). "Moreover, 25% of polycythemia vera, 29.5% of ET, and 48.1% of PMF were negative for all three mutations (JAK2V617F, MPL, and CALR)." (PMID 26375990, 2015).
Thrombocytosis (45 papers, 2014 to 2025). Increased numbers of platelets in the peripheral blood. "Laboratory tests revealed marked thrombocytosis (>1,000,000/μL) and a CALR mutation, confirming a diagnosis of ET." (PMID 40278216, 2025). "Studies on patients with thrombocytosis have revealed a correlation between CALR mutations and EPO levels." (PMID 40568201, 2025). "Conversely, DP5, enriched with CALR mutations, predominantly included patients with ET presenting with isolated thrombocytosis." (PMID 39682306, 2024). "Especially mutations in JAK2 (P < 0.001) and CALR (P = 0.003) were enriched in individuals with thrombocytosis." (PMID 36698617, 2023). "Antenatal IFN was used in five pregnancies: two with CALR mutation and extreme thrombocytosis (white blood cell (WBC) above 2000 × 109/L), one with JAK2 mutation and prior thrombosis, and two with JAK2 mutation and prior second trimester pregnancy losses." (PMID 36819152, 2023). "In particular, while patients with PMF and type 2-like mutation mimicked the ET phenotype in terms of thrombocytosis, they tended to exhibit a higher leukocyte count and CALR mutant burden than patients with ET and the same CALR mutant type." (PMID 36359414, 2022). "These heterozygous CALR mutants developed a transplantable ET-like disease with marked thrombocytosis associated with increased and morphologically abnormal MK and increased HSC numbers." (PMID 32842500, 2020). "By contrast, JAK2-selective inhibitor fedratinib has only minimal inhibitory effects on normal thrombopoiesis but has modest and dose-independent inhibitory effect on thrombocytosis caused by mutant CALR." (PMID 27716741, 2016). "Collectively, these findings indicated that the expression of mutant CALR causes thrombocytosis through an mpl-dependent mechanism in zebrafish." (PMID 27716741, 2016). "On the basis of the data from the murine and zebrafish animal models, the causative relationship between CALR mutations and thrombocytosis can be confirmed, and CALR mutations have been established as one of the driver mutations in MPNs." (PMID 27716741, 2016). "Indeed, CALR-mutated patients, as first reported by Klampfl and Nangalia, are younger and characteristically show marked thrombocytosis accompanied by relatively lower hemoglobin and leukocyte counts when compared with JAK2-mutated cases." (PMID 41228192, 2025). "We may conclude that the large proportion of community-based individuals with thrombocytosis in combination with JAK2/MPL/CALR mutations represented premalignant or underdiagnosed cases of MPN." (PMID 36698617, 2023). "However, the presence of reactional thrombocytosis does not formally exclude the hypothesis of underlying ET hence the importance of detecting the three driver mutations (JAK2, MPL and CALR) in persistent thrombocytosis." (PMID 36980287, 2023). "The higher frequency of CALR mutations in prePMF compared to ET (35·8% vs 17·8%, P <·001) might contribute to the high level of platelet count observed in prePMF and to the higher frequency of extreme thrombocytosis (> 1000 × 109/L) observed in prePMF." (PMID 29254200, 2017). "Given his marked thrombocytosis and CALR-driven platelet dysfunction, the thrombotic event was most likely driven by the prothrombotic and inflammatory milieu associated with ET, despite the absence of other identifiable triggers." (PMID 40278216, 2025). "Mutations in spliceosome-associated genes were enriched in cases with thrombocytopenia compared with matched controls, whereas MPN-associated mutations (JAK2, CALR, MPL) were enriched in cases with thrombocytosis." (PMID 36698617, 2023). "A total of 48.5% of JAK2/MPL/CALR mutant cases with thrombocytosis were diagnosed with a hematological malignancy at follow-up." (PMID 36698617, 2023). "The combination of thrombocytosis and JAK2/MPL/CALR mutations is highly suggestive for undiagnosed MPN or a premalignant condition, while other gene mutations seem to have no relevance in these cases." (PMID 36698617, 2023).
Thrombocytosis (continued). "Individuals with thrombocytosis, compared with their matched controls, had a higher prevalence of JAK2 (12.8% vs 1.1%; P < 0.001) (all V617F mutations) and CALR mutations (4.7% vs 0.0%; P = 0.003)." (PMID 36698617, 2023). "Mutations in genes associated with MPNs (JAK2, CALR, and MPL) were identified in 32 of 172 (18.6%) individuals with thrombocytosis versus 2 of 175 (1.1%) in their matched controls." (PMID 36698617, 2023). "Mutations in MPN-associated genes JAK2, CALR and MPL were observed at considerably high frequency in individuals with thrombocytosis." (PMID 36698617, 2023). "Knock-in mice expressing mutant CALR (CALRdel/del) develop marked thrombocytosis, increased megakaryopoiesis, and an expansion of immunophenotypically defined HSCs." (PMID 35767701, 2022). "Conversely, MHCIIlo HSCs displayed increased megakaryocytic potential and were preferentially expanded in CALR mutant mice with thrombocytosis." (PMID 35767701, 2022). "In our study, type 1-like CALR mutation was predominant in PMF compared with ET, and patients with MPN and type 2-like mutation were characterized by profound thrombocytosis than those with type 1-like mutation." (PMID 36359414, 2022). "Studies on animal models have shown that del52 mutants develop a more severe thrombocytosis than ins5 CALR mutants." (PMID 33806036, 2021). "As the indirect stimulation on the JAK-STAT pathway by CALR mutation, the MPL mutation on hematopoietic stem cells leads to extreme thrombocytosis." (PMID 34684081, 2021). "Other factors influencing the magnitude of thrombocytosis are the amount of CALR mutants and the ratio of CALR mutants to CALR wild type (wt)." (PMID 33806036, 2021). "This suggests that the magnitude of thrombocytosis is dependent on the amount of CALR mutants and probably on the ratio of CALR mutant to CALR wt." (PMID 32985500, 2020). "And ruxolitinib ameliorated the thrombocytosis in CALR mutant mice and attenuated the increase in number of BM megakaryocytes and HSCs, revealing a vital role for MPL and STAT5 activation in CALR mutation-induced MPN." (PMID 30237983, 2018). "Thrombocytosis is either due to GOF alterations that activate MPL signaling (MPL, JAK2, CALR) or due to LOF mutations of negative regulators of this pathway (CBL, LNK)." (PMID 28955303, 2017). "Whereas treatment with fedratinib only had minimal inhibitory effect on the number of CD41+ thrombocytes in uninjected control embryos, and had a modest and significant dose-independent inhibitory effect on mutant CALR-induced thrombocytosis." (PMID 27716741, 2016). "Although CALR-positive ET is typically associated with a lower thrombotic risk than JAK2-positive cases, thrombotic complications can still occur, especially in the context of extreme thrombocytosis, older age, or other modifying factors." (PMID 40278216, 2025). "However, in routine practice, many cases of polyglobulia and thrombocytosis lack either the typical MPN mutations in the JAK2, CALR or MPL genes, the histopathological features of MPN, or both." (PMID 37639050, 2023). "In competitive transplant calreticulin‐mutant mouse models, 10 weeks of treatment with INCA033989 prevented thrombocytosis and significantly decreased the numbers of CALR‐mutant stem and progenitor cells, as well as megakaryocytes in the bone marrow, without affecting cellularity of wild‐type mice." (PMID 37551061, 2023). "Although the oncogenic mechanism of the mutant CALR is not fully elucidated, it has been hypothesized that the mutations enhance the binding capacity of CALR to TPOR, whose hyperactivation leads to enhanced megakaryocyte proliferation and thrombocytosis." (PMID 33672997, 2021). "The mutation of the CALR gene on exon 9 of chromosome 19 is found in up to 25% of cases of ET or MF; this mutation indirectly stimulates the JAK-STAT pathway, increasing MPL activity in hematopoietic stem cells with consequent thrombocytosis." (PMID 34684081, 2021).
Thrombocytosis (continued). "All CALR mutant-expressing mice rapidly developed thrombocytosis due to MK hyperplasia." (PMID 32842500, 2020). "Finally, the co-existence of additional CALR/MPL or JAK2 exon 14 and exon 12 mutations was routinely excluded in all cases of thrombocytosis or polyglobulia, respectively, that present with a low JAK2V617F AB." (PMID 28422729, 2017). "Interestingly, CALR mutations are recently found to activate the JAK-STAT signaling through a MPL-dependent mechanism, and cause thrombocytosis both in vitro and in vivo." (PMID 28415571, 2017). "Because CALR is physiologically functioning as a chaperone for MPL, it is reasonable to speculate that mutant CALR may interact directly with mpl to cause thrombocytosis in zebrafish." (PMID 27716741, 2016). "Our data suggested that fedratinib can normalize the thrombocytosis caused by the expression of mutant CALR and does not cause significant thrombocytopenia in zebrafish model." (PMID 27716741, 2016). "Moreover, mutant CALR enhanced megakaryocytic differentiation and pro-platelet formation which is in line with and extends the recent demonstration that CALR mutants induce thrombocytosis in vivo." (PMID 27740635, 2017). "In addition to ET and PMF patients, CALR mutations have also been observed in 3(13.0%) of 24 patients with refractory anemia with ringed sideroblasts and marked thrombocytosis; none of the 3 patients had JAK2 or MPL mutations." (PMID 27486987, 2016). "We have shown that expression of the CALR-del52 mutant disturbs thrombopoiesis and increases the number of HSPCs in the CHT followed by significant thrombocytosis in the zebrafish embryo." (PMID 27716741, 2016). "A total of forty-one pediatric patients with elevated platelet counts diagnosed with ET (nine with CALR driver mutation, eleven with JAK2, thirteen triple-negative, and one dual-negative (TN)) or secondary thrombocytosis (five) were recruited." (PMID 41465385, 2025). "In CML patients, the persistence or occurrence of thrombocytosis, despite WBC decrease and good molecular BCR::ABL1 response under TKI, should alert clinicians to perform molecular screening for Ph-negative MPN, including JAK2, MPL, and CALR mutations." (PMID 38596359, 2024). "Importantly, in these patients, anemia, leukocytosis, and thrombocythemia are ascribed to their chronic inflammatory disease or cancer and, accordingly, they are not normally screened for JAK2V617F, CALR, or MPL mutations." (PMID 26604428, 2015). "Even though the oncogenic mechanism of the CALR mutations is not fully clarified, it appears that the mutations enhance the binding of CALR to the thrombopoietin receptor (TPO-R), resulting in the activation of TPO-R and ensuing megakaryocyte proliferation and thrombocytosis." (PMID 32630667, 2020).